IGFBP2 (insulin like growth factor binding protein 2)
Diseases named in the same sentence as IGFBP2 in open-access papers (continued):
Sharing a sentence is not in itself a finding about the gene and the disease.
Obesity (continued). "IGFBP2 can inhibit adipocyte differentiation in vitro, and when overexpressed in vivo, mice are protected from developing age- and diet-induced obesity and insulin resistance." (PMID 24023810, 2013). "Increased IGFBP-2 concentrations are protective against the development of obesity and improve insulin sensitivity, while higher IGFBP-1 concentrations are associated with lower insulin levels." (PMID 23516412, 2013). "Recent studies have shown that overexpression of Igfbp2 protects against the development of obesity and improves insulin sensitivity." (PMID 20808936, 2010). "We further discuss IGFBP2 within an autocrine, paracrine, and endocrine framework, with emphasis on its effects on glucose handling, lipid metabolism, insulin sensitivity, and metabolic adaptation in obesity-related disease states." (PMID 42095224, 2026). "IGFBP1 and IGFBP2 were consistently reduced in children with obesity, along with adiponectin." (PMID 39972214, 2025). "Interestingly, IGFBP2-overexpressing transgenic mice are protected from both high-fat diet induced obesity and age-induced insulin resistance with improved glucose tolerance." (PMID 38918843, 2024). "The association between serum IGFBP-2 levels and survival was not significant after excluding patients with obesity and patients with cirrhosis." (PMID 38255230, 2024). "As IGFBP2 is reported to exert a protective role against obesity and diabetes onset, and glucose metabolism is more rapidly affected in males after HFD intake, one might speculate that the novel HFD exposure results in activation of protective mechanisms." (PMID 37580448, 2023). "The role of IGFBP2 in glucose intake, insulin sensitivity, including insulin resistance, lipid profile, and obesity may contribute to metabolic syndrome." (PMID 33498859, 2021). "A reduction in IGFBP2 has been reported in both male and female patients with obesity." (PMID 34975768, 2021). "In addition, blood glucose after a glucose tolerance test was significantly lower in IGFBP2 than wild-type mice on both types of diet, suggesting that IGFBP2 protects against obesity and insulin resistance." (PMID 33498859, 2021). "Furthermore, IGFBP‐2 is known to be suppressed by GH, insulin, and obesity and has been positively correlated with insulin sensitivity." (PMID 34811874, 2021). "We hypothesize mechanisms of IGFBP2 on the development of obesity and insulin resistance in an insulin-independent manner, which meant that could be evaluated as a therapeutic target." (PMID 33498859, 2021). "Adequate serum levels of IGFBP2 inhibit differentiation of preadipocytes, and further hyperplasia and hypertrophy of visceral adipose tissue in both dependent and independent actions, which results in preventing obesity state." (PMID 33498859, 2021). "It is worth pointing out that IGFBP2 could prevent obesity through inhibition of adipogenesis according to dependent and independent action models." (PMID 33498859, 2021). "IGFBP2 has potent beneficial therapeutic action in obesity and insulin resistance." (PMID 33498859, 2021). "IGFBP2 is proposed to be an antidiabetic factor, protecting against obesity onset." (PMID 33202914, 2020). "Igfbp2 promoter methylation in whole blood cells was shown to correlate with an increased type 2 diabetes risk in patients without obesity." (PMID 32532003, 2020). "This is supported by a study using a mouse model of diet-induced obesity, where hypermethylation of the Igfbp2 promoter and reduced Igfbp2 gene expression in early life correlated with the development of fatty liver and impaired glucose metabolism in adolescence." (PMID 32532003, 2020). "Furthermore, in the intervention study presented here, in men with obesity the significant reduction of BMI two years after surgery was accompanied with the reduction of fatty liver and serum IGFBP2 concentration." (PMID 32532003, 2020). "IGFBP-2 is secreted by white adipocytes and contributes to the prevention of diet-induced obesity." (PMID 32380764, 2020).
Obesity (continued). "In addition to the significant differences observed in serum adipokines, fasting glucose levels, insulin levels, and glucose tolerance, obesity was also associated with elevated serum levels of IGF-1, IGF-1/IGFBP2, and IGF-1/IGFBP3 in HFD-Obese mice." (PMID 30867005, 2019). "The high Vitamin D status correlated with the serological upregulation of IGFBP-2 in males and IGFBP-3 in females with obesity and may constitute surrogate markers of risk reduction of cardiometabolic disease." (PMID 30287811, 2018). "IGFBP-2 is reported to be a key regulator of metabolic diseases, such as diabetes and obesity." (PMID 29422987, 2017). "Actually, high serum levels of IGFBP-2 appear to protect against obesity and type 2 diabetes." (PMID 27899768, 2016). "With respect to breast cancer and perhaps other obesity-related cancers such as colorectal cancer, the proliferative potential of IGFBP-2 may be countered by its role in obesity and adipocyte biology." (PMID 26106415, 2015). "In addition, in animal models IGFBP-2 overexpression is protective against obesity and also protects against the development of insulin resistance and increases glucose sensitivity." (PMID 26106415, 2015). "Interestingly, “beiging” of eWAT correlated with increased expression of Wnt10b and IGFBP2, two endocrine/paracrine factors recognized for their anti-obesity and bone anabolic activity." (PMID 24810249, 2014). "Notably, Igfbp2 and Serpina11 were associated with pathways such as ‘Extracellular space’ in the broader RYGB-Induced analysis, suggesting potential roles in reshaping extracellular or signaling environments to reverse obesity-linked liver perturbations." (PMID 41598416, 2026). "Furthermore, it is noteworthy to note that IGFBP2 has a protective role in obesity." (PMID 33498859, 2021). "To examine whether circulating IGFBP2 levels are altered during the course of fatty liver disease progression in humans, we measured IGFBP2 serum concentration in men with class III obesity, with histology confirmed hepatic pathological state (HepObster study)." (PMID 32532003, 2020). "Plasma IGFBP-2 levels correlate with insulin resistance and could be used as a biomarker of insulin sensitivity and may play an important role in the pathogenesis of obesity complications in early life." (PMID 30392760, 2019). "In addition, given the anti-obesity and anti-diabetic properties of IGFBP-2, we suggest that IGFBP-2 might interact with PPAR-γ2 to protect against insulin resistance in obese individuals." (PMID 31547433, 2019). "Of these, insulin-like growth factor binding protein 2 (IGFBP2) was potentially the most interesting, as its regulation of insulin appears to have implications both in epithelial growth and differentiation in cancer and in protection from obesity and insulin resistance." (PMID 27088090, 2016). "Similarly, the influence of obesity has been examined with respect to the levels of IGFBP2, with lower levels observed in obese patients, which has been proposed to be a result of hyperinsulinemia, with insulin suppressing IGFBP2 expression." (PMID 25774149, 2015). "Moreover, in obesity, IGFBP-2 was shown recently to reflect long-term insulin sensitivity." (PMID 22242132, 2011). "BMI-predictive proteins included established obesity markers and obesity-related proteins, including adiponectin, CRP, IGFBP1, IGFBP2, PRG4, SHBG, apolipoproteins (APOA4, APOF) and inflammatory response proteins (A2M, APCS, LBP, HSPG2, HP, AOC3, ITGB1, VNN1)." (PMID 39972214, 2025). "Insulin-like growth factor-binding protein 2 (IGFBP2) is secreted by white adipocytes and contributes to the prevention of diet-induced obesity and age-related insulin resistance." (PMID 35646056, 2022).
Obesity (continued). "Therefore, various biopharmaceutical engineering approaches may be adopted to develop IGFBP2 analogues and mimetics with improved physiological properties in obesity and insulin sensitivity, pharmacokinetic profiles and potency that are suitable for future clinical development." (PMID 33498859, 2021). "IGFBP2 is the second most abundant IGF-binding protein in the circulation and has been suggested to be protective against obesity and to improve glucose tolerance on a HFD." (PMID 32849298, 2020). "Circulating IGFBP2, one of the most abundant IGFBPs in serum, is suggested to play a role in protection against HFD-induced obesity and diabetes onset." (PMID 33202914, 2020). "The increase in Igfbp2 secretion by VIS high APs and the abundance of these cells in obesity prompted us to examine its level in the serum of lean and obese (ob/ob) mice." (PMID 31597091, 2019). "Thus, IGFBP-2 might protect against the development of obesity and insulin resistance in humans." (PMID 31547433, 2019). "In conclusion, IGFBP-2 and IGFBP-3 were found to correlate with vitamin D status in males and female adults with obesity, respectively." (PMID 30287811, 2018). "Furthermore, our study confirmed that the relationship between IGFBP2 and CAP remained consistent across both the overall cohort and the subgroup excluding individuals with severe obesity." (PMID 40608848, 2025). "The same conclusion was corroborated in a subgroup analysis excluding individuals with severe obesity, indicating that IGFBP2 is unlikely to be a major contributor to the hepatic fibrosis process." (PMID 40608848, 2025). "In particular, genes such as IGFBP2 and CASP1, with functions related to obesity and metabolism, may explain some of our previous findings of metabolically dysregulated fibroblasts in OA synovial tissue from obese patients." (PMID 38918843, 2024). "Obesity leads to enhanced circulating levels of insulin, IGF-I, IGF-II and IGF-binding proteins (IGFBP-3), while reducing levels of the low molecular weight IGF-binding proteins (IGFBP-1, IGFBP-2)." (PMID 38260836, 2023). "Evidence from observational and in vitro studies suggests that insulin growth-factor-binding protein type 2 (IGFBP2) is a promising protein in non-communicable diseases, such as obesity, insulin resistance, metabolic syndrome, or type 2 diabetes." (PMID 33498859, 2021). "As previously indicated, IGFBP2 is reported to protect against diabetes and obesity onset and here a negative correlation between circulating IGFBP2 and insulin, glycemia, leptin and body weight was found in males." (PMID 34975768, 2021). "Moreover, because the IFG secretion and binding were usually inhibited with the onset of excessive fat storage, the increased expression of Igfbp2 and the regulation of IGF binding function by 5% carrageenan suggested the relieving of obesity." (PMID 34760253, 2021). "In humans, we found lower IGFBP2 serum concentration in obese men with NAFL or NASH compared to control men without obesity." (PMID 32532003, 2020). "Even in patients without obesity, a negative association between FLI and IGFBP2 serum concentration is accompanied by an increase of BMI and waist circumference indicating a gradual decrease of IGFBP2 with the degree of fatty liver and adipose tissue function." (PMID 32532003, 2020). "Serum levels of free IGF1 and IGFBP3, but not of total IGF1, are reported to be higher and IGFBP2 lower in children with obesity compared to control children." (PMID 32849298, 2020). "Obesity-related hyperinsulinaemia increases IGF-1 and inhibits IGFBP-2 secretion." (PMID 32586279, 2020). "In another study, administration of synthetic peptides mimicking the heparin binding domains of the native protein replicated the inhibitory effects of IGFBP-2 on obesity but did not affect glucose tolerance." (PMID 30392760, 2019).
Obesity (continued). "Besides the annotated body weight relevant genetic elements, such as QTL rs3662726, genes Mogat1, Igfbp2, and Cyp2c37, mgRF provided valuable hypotheses on putative, novel genetic elements and their interactions that are potentially important for body weight and obesity." (PMID 23505362, 2013). "Like adipocytes in obesity, CAAs secrete significantly higher levels of motility factors such as CCL2, CCL5, autotoxin (ATX), as well as proinflammatory cytokines such as IL-1β, IL-6, TNF-α, VEGF, insulin-like growth factor binding protein-2 (IGFBP-2), and leptin but much less of adiponectin." (PMID 33916703, 2021). "IGFBP2's role in CVD may be multifactorial, with associations also shown with intima-media thickness and myocardial infarction, while data on cardiometabolic endpoints such as obesity and metabolic syndrome paradoxically show negative correlations with IGFBP2 in literature." (PMID 35722087, 2022). "Because no data about the interaction of IGFBP-2 and PPAR-γ have been reported, the evidence cannot rule out the importance of PPAR-γ2–IGFBP-2 interaction, especially in insulin resistance and obesity." (PMID 31547433, 2019).
breast carcinoma (73 papers, 2005 to 2025). "In summary, IGFBP-2 is a survival factor for breast cancer cells that is associated with enhancement of the DNA repair mechanism." (PMID 38893232, 2024). "High mRNA expression of IGFBP2 is associated with better survival in patients with breast cancer and poor survival in glioblastoma patients." (PMID 37088808, 2023). "Based on IGFBP2 positivity of breast cancers, a DNA vaccine was designed, encoding HER-2/neu, IGFBP2 and insulin-like growth factor 1 receptor (IGF1R) as tumor associated antigens and it proved to be effective in preclinical trials." (PMID 32133294, 2020). "Prior epidemiologic studies have reported inverse associations between IGFBP-2 and risk of atypical hyperplasia and postmenopausal breast cancer." (PMID 31337427, 2019). "Epidemiological studies have not extensively explored the associations of other IGFBPs (IGFBP 4, 5, 6, and 7) and breast cancer risk, with the exception of IGFBP-2, where findings have been inconsistent." (PMID 31337427, 2019). "Other studies have reported null findings for circulating IGFBP-2-associated breast cancer risk relationships." (PMID 31337427, 2019). "Overexpression of IGFBP2 has been associated with resistance to paclitaxel and antihormone therapy in breast cancer." (PMID 28977895, 2017). "The inverse association between serum IGFBP-2 levels and breast cancer risk observed previously seems to be restricted to women who were not using HT and to those women who are overweight or obese." (PMID 26106415, 2015). "An early study investigated the association between IGFBP-2 and postmenopausal breast cancer and found a reduction in risk with increasing serum IGFBP-2, although further studies were not able to confirm these findings." (PMID 26106415, 2015). "IGFBP2 expression was associated with overall and breast cancer mortality (HRmort = 10.96, 95% CI: 2.18–55.19 and HRmort = 35.75, 95% CI: 3.64–350.95, respectively)." (PMID 25619494, 2015). "Increased IGFBP2 expression has been reported in many malignancies and has been linked to chemoresistance in ovarian cancer, breast cancer, colon cancer, lung cancer, prostate cancer, glioma and leukemia." (PMID 26317790, 2015). "Increased expression of IGFBP2 caused by loss of miR-126 was found to promote breast cancer cell metastasis by recruitment of endothelial cells to the cancer site through up-regulating the insulin growth factor 1 receptor (IGF1R) signaling pathway." (PMID 24069370, 2013). "Most significantly, our data shows for the first time that the concomitant over expression of IGFBP2 and β-catenin in breast cancer is associated with increased incidence of lymph node metastasis." (PMID 23767917, 2013). "To gain further insights into the role of IGFBP2 in breast cancer, we have attempted to identify the molecular players in IGFBP2 associated tumorigenesis in breast cancer." (PMID 23767917, 2013). "Among BRCA2 carriers, an LD block in IGFBP2 (global P = 0.0145) was found to be associated with the time to breast cancer diagnosis." (PMID 19843326, 2009). "IGFBP-2 also upregulates PD-L1, and facilitates nuclear EGFR accumulation; thus it may be hypothesized that the targeting of IGFBP-2 by miR-873 is also implicated in both stemness and chemoresistance in breast cancer." (PMID 35597813, 2022). "Additionally, high glucose level in breast cancer patients has been associated with elevated IGFBP2 levels and subsequently with chemo-resistance, highlighting the role of IGFBP2 in modulating a cancer cell’s response to chemotherapy." (PMID 34225729, 2021). "However, IGFBP-2 expression in breast tissue was associated with better survival among more than 885 women with primary breast cancer with possible effect modification by BMI." (PMID 30497427, 2018).